LNCTAM34A (long non coding transcriptional activator of miR34a)
Synonyms: GUARDIN; TP53LC18; LINC01759
Gene: Long non-coding RNA gene on chromosome 1 (9,181,588 to 9,198,023, forward strand). Ensembl gene ENSG00000234546.
Diseases named in the same sentence as LNCTAM34A in open-access papers:
LNCTAM34A is named in the same sentence as 3 diseases in open-access papers, as found by Europe PMC text mining. Sharing a sentence is not in itself a finding about the gene and the disease.
LNCTAM34A shares sentences with these, for which no sentence is quoted: cancer (6 papers); colon tumors (1); tumor (1).